GNA11 (G protein subunit alpha 11)
Diseases named in the same sentence as GNA11 in open-access papers (continued):
Sharing a sentence is not in itself a finding about the gene and the disease.
cutaneous melanoma (27 papers, 2012 to 2025). A primary melanoma arising from atypical melanocytes in the skin. "GNAQ and GNA11 mutations are prevalent in primary CNS melanoma but differ from cutaneous melanoma (CM), in which BRAF, NRAS, KIT, and NF-1 mutations are more common." (PMID 41536409, 2025). "Our results suggested that oncogenic mutations in GNAQ and its closely related homolog, GNA11, are rarely found in cutaneous melanoma because the epidermal microenvironment causes Gαq/11 signaling to inhibit melanocytes." (PMID 34939927, 2021). "PTEN, KIT, and GNAQ/GNA11 mutations are among the rarest in cutaneous melanomas." (PMID 37373134, 2023). "UM tumors are frequently detected with mutations in GNA11, GNAQ, EIF1AX, BAP1, and SF3B1 instead of the typical mutations associated with cutaneous melanoma." (PMID 40283643, 2025). "In this regard, GNAQ/GNA11-driven UM is similar to cutaneous melanomas that are driven by other oncogenes." (PMID 41154654, 2025). "We present the case of a 23-year-old pregnant woman who was found to have likely primary malignant melanoma of the lip that metastasized to the left jaw, neck, breast, lungs, and ovaries and was found to be positive for both the BRAF-MLL3 and GNA11 mutation." (PMID 37284406, 2023). "Compared to cutaneous melanoma (CM), which mainly harbors BRAF or NRAS mutations, UM predominantly harbors GNAQ or GNA11 mutations." (PMID 35804863, 2022). "We validated previous reports that the commonly known mutations in cutaneous melanoma, including BRAF, NRAS, NF1, GNAQ and GNA11, were rarely mutated in mucosal melanomas." (PMID 30847022, 2019). "The majority of human cutaneous melanomas are driven in part by constitutive activation of the MAPK pathway through mutation of genes such as BRAF, NRAS, NF1, KIT, GNAQ, and GNA11, often in a mutually exclusive pattern." (PMID 30188888, 2018). "Our panel also included five cutaneous melanoma cell lines wild type for mutations in NRAS, BRAF, GNAQ and GNA11 and only one was highly sensitive to TAK733 with IC50s below 1 nM, while two were considered sensitive with IC50 less than 10 nM." (PMID 22515704, 2012). "As an example, GNA15 (encoding Gαq subunits) is significantly mutated in skin melanomas that do not often carry GNAQ or GNA11 mutations." (PMID 32532044, 2020). "However there is some overlap in tumor biology as ~80% of blue nevi, which are benign melanocytic tumors of the skin, also harbor GNAQ or GNA11 mutations, and BAP1 mutations can be found in both cutaneous nevi and cutaneous melanoma." (PMID 23694694, 2013). "It is widely recognized that, unlike cutaneous melanoma, the vast majority (>90%) of UM cases are driven by activating mutations in the GNAQ and GNA11 genes, which encode the alpha subunits of heterotrimeric G-proteins." (PMID 41154654, 2025). "In line with earlier observations in skin melanoma cells, these effects were independent of the mutational status (GNAQ, GNA11, BAP1, BRAF and NRAS) of the UM and CM cell lines." (PMID 34508176, 2022). "Although GNAQ and GNA11 mutations have been reported in a cutaneous melanoma case and a cell line from cutaneous melanoma, there are no data to demonstrate GNAQ or GNA11 mutations in mucosal melanoma." (PMID 25030020, 2014).
familial hypocalciuric hypercalcemia (13 papers, 2016 to 2026). Familial hypocalciuric hypercalcemia (FHH) is a generally asymptomatic genetic disorder of phosphocalcic metabolism characterized by lifelong moderate hypercalcemia along with normo- or hypocalciuria and elevated plasma parathyroid hormone (PTH) concentration. "Of interest, different mutations in GNA11 in the germline leading to altered sensitivity of cells to extracellular calcium concentrations have been described in autosomal dominant hypoparathyroidism and hypocalciuric hypercalcemia, respectively." (PMID 26778290, 2016). "FHPT may also present as non-syndromic PHPT, which includes familial hypocalciuric hypercalcemia (FHH) forms (caused by variants of CASR, GNA11, or AP2S1), neonatal severe hyperparathyroidism, and other forms caused by several genes classified as familial isolated hyperparathyroidism (FIHP)." (PMID 37810884, 2023).
Hypercalcemia (12 papers, 2017 to 2025). An abnormally increased calcium concentration in the blood. "Germline pathogenic variants in GNA11 are also associated with dominantly inherited hypo‐ and hypercalcemia, while those in PLCB4 with dominantly and recessively inherited auriculocondylar syndrome." (PMID 39344744, 2025). "Over a 10‐year period, we identified 37 different GNA11 variants in >1200 probands referred for investigation of a genetic cause of their hypercalcemia or hypocalcemia." (PMID 36970776, 2023). "In summary, we identified 37 different GNA11 variants in 1226 probands undergoing investigation for a genetic cause of their hypercalcemia or hypocalcemia over a 10‐year period." (PMID 36970776, 2023). "Between 2013 and 2022, DNA sequence analysis identified 37 different GNA11 variants in 1226 probands referred for investigation of a genetic cause of their hypercalcemia (n = 1014) or hypocalcemia (n = 212)." (PMID 36970776, 2023). "In a 10‐year period, we identified 37 different germline GNA11 variants in >1200 probands referred for investigation of genetic causes for hypercalcemia or hypocalcemia, comprising 14 synonymous, 12 noncoding, and 11 nonsynonymous variants." (PMID 36970776, 2023). "An in vivo model is not available for FHH2, although mice with parathyroid-specific combined ablations of both the Gna11 and Gnaq (encoding Gαq) genes have previously been reported to develop marked hypercalcemia and hyperparathyroidism." (PMID 29046478, 2017). "Thus, this study identified likely disease‐causing GNA11 variants in <1% of probands with hypercalcemia or hypocalcemia and highlights the occurrence of GNA11 rare variants that are benign polymorphisms." (PMID 36970776, 2023). "Before age 8, almost all cases of PTH-dependent hypercalcemia are caused by familial hypocalciuric hypercalcemia (mostly from mutation in CASR, AP2S1, or GNA11) or by neonatal severe primary hyperparathyroidism, both of which have near 100% penetrance for hypercalcemia already in the neonate." (PMID 30065698, 2018). "Thus, Gna11+/195G mice had mild hypercalcemia in association with normal plasma PTH concentrations; they also had no alterations in the plasma concentrations of phosphate and creatinine, or in alkaline phosphatase activity, which is consistent with the reported phenotype of FHH2 patients." (PMID 29046478, 2017). "Both Gna11+/– and Gna11–/– mice demonstrated hypercalcemia and mildly raised parathyroid hormone levels, consistent with FHH." (PMID 38530370, 2024). "Therefore, increased serum FGF23 levels are expected to stimulate renal calcium reabsorption and further exacerbate hypercalcemia in our Gna11-KO mice." (PMID 38530370, 2024). "To determine whether the hypercalcemia of Gna11+/195G and Gna11195G/195G mice may be improved by in vivo calcimimetic treatment, we administered cinacalcet to WT and mutant mice." (PMID 29046478, 2017). "Thus, hypercalcemia may account for the elevated serum iFGF23 and skeletal Fgf23 mRNA levels observed in Gna11+/– mice." (PMID 38530370, 2024). "The phenotype of the Trpc1–/– mice is consistent with that of FHH in humans, and the possibility that mutations in the TRPC1 gene may be a cause of hypercalcemia in some patients with FHH who did not have CASR, GNA11, or AP2S1 mutations was therefore explored." (PMID 32213715, 2020).
Hypocalcemia (9 papers, 2016 to 2023). An abnormally decreased calcium concentration in the blood. "These patients express activating mutations in CaSR, or in G protein 11 (GNA11), which cause hypocalcemia, inappropriately low PTH levels, and moderate hyperphosphatemia." (PMID 31619668, 2019). "The only variant identified in a gene previously associated with hypocalcemia, was a heterozygous G>A transition at nucleotide c.1018 (c.1018G>A), located in exon 7 of the GNA11 gene." (PMID 26818911, 2016). "The similar clinical presentation between familial isolated hypoparathyroidism in humans and equine idiopathic hypocalcemia led to the hypothesis that a coding variant within PTH, GCM2, CASR, GNA11 or TRPM6 would be associated with idiopathic hypocalcemia of TB foals." (PMID 32986719, 2020). "Our study has revealed Dsk7 mice to have hypocalcemia and reduced PTH concentrations, which are caused by a gain-of-function Gna11 mutation that leads to upregulation of CaSR-mediated Ca2+i and MAPK signaling responses." (PMID 28194447, 2017). "Similarities between familial isolated hypoparathyroidism in humans and the refractory hypocalcemia observed in Thoroughbred foals led to the hypothesis that genetic variants in PTH, GCM2, CASR, GNA11 or TRPM6 may be responsible for the disease in the horse." (PMID 32986719, 2020). "However, it remains unclear whether this calcilytic may rectify the hypocalcemia associated with ADH2, and mouse models that harbor Gna11 mutations in association with hypocalcemia have not been reported to be available for such in vivo studies." (PMID 28194447, 2017).
mucosal melanoma (8 papers, 2014 to 2025). A melanoma that arises from a mucosal site. "However, GNAQ or GNA11 mutations have not been reported in mucosal melanoma." (PMID 25030020, 2014). "These genetic alterations are rarely observed in cutaneous or mucosal melanomas, suggesting that GNAQ and GNA11 may be involved in the early migration of melanocytes during embryogenesis, given GNAQ is important in melanocyte survival during early neural crest development." (PMID 41303082, 2025).
breast carcinoma (7 papers, 2012 to 2023). "Notably, several breast cancer cell, colon cancer cell and lung cancer cell lines presented robust nPD-L1 signals, which were free of classic mutations (e.g., GNA11/GNAQ/BAP1) in UM." (PMID 36977660, 2023). "Studies suggested that the methylation of GNA11 resulted in reduced mRNA expression in breast cancer, which was of great help in the growth of human breast cancer cells." (PMID 34568004, 2021). "But, unlike an oncogene downregulation of GNA11 was observed in human breast cancers." (PMID 35620468, 2022). "Similarly, methylation of a CGI in intron 1 of GNA11 does not show a clear correlation with its decreased expression in human breast cancers." (PMID 26030766, 2015).
metastatic disease (7 papers, 2013 to 2026). "Once more, regarding these results, the authors proposed a bias towards GNA11 p.Q209L mutations in metastatic disease." (PMID 35804836, 2022). "In contrast to the tissue samples, TS only identified mutations in GNA11 [variant allele frequency (vaf) = 0.92%] and BAP1 (vaf = 1.57%) at one plasma timepoint in 1 patient with metastatic disease 6 months after brachytherapy (Patient 09—6 months)." (PMID 36860651, 2023). "There has been increasing attention on the impact of activating genetic mutations in GNAQ and GNA11, loss-of-function mutations in the tumor suppressor gene BAP1, and recurrent mutations at codon 625 of SF3B1 on the advancement of UM towards metastatic disease." (PMID 39061150, 2024).
hemangioma (6 papers, 2021 to 2025). A benign vascular lesion characterized by the formation of capillary-sized or cavernous vascular channels. "Mutations in PIK3CA, TEK, GNAQ, and GNA11 have been identified in various types of vascular malformations and hemangiomas." (PMID 40428263, 2025). "In this article, we investigate the role of GNAQ and GNA11 mutations across varied disorders (e.g., UM, skin blue nevi, and hemangiomas), emphasizing the shared pathogenic mechanisms that connect them despite their differing clinical manifestations." (PMID 39518110, 2024). "Thrombotic hemangioma with organizing/anastomosing features (THOA) is a newly identified variant within the spectrum of hemangiomas that harbor mutations in the guanine nucleotide-binding protein alpha subunit (GNA) genes (like GNAQ or GNA11)." (PMID 39360118, 2024). "For example, MEK inhibitors may be useful in managing vascular malformations or benign proliferations like hemangiomas associated with GNAQ/GNA11 mutations." (PMID 39518110, 2024). "The results of these studies implicate that the essential mechanism underlying the pathogenesis of anastomosing hemangioma is related to GNAQ mutations, as well as its paralogues: GNA11 and GNA14." (PMID 39518110, 2024). "Our study identifies GNA14 Q205, GNA11 and GNAQ Q209 mutations as being the most common and mutually exclusive mutations in benign hemangiomas." (PMID 34040639, 2021). "The frequency of GNA gene mutations (GNAQ, GNA11 and GNA14) was highest with more than 52% in cases diagnosed as cherry (or senile) hemangioma." (PMID 34040639, 2021). "GNAQ, GNA11, and GNA14 (particularly GNA14 Q205L) mutations, which were mutually exclusive, were identified in approximately half of the cherry hemangiomas and cherry hemangioma-like hemangiomas." (PMID 39518110, 2024). "For cherry, congenital, anastomosing hemangioma, GNA14, GNA11 and GNAQ alterations have been described to be the most common alterations in these subtypes." (PMID 34040639, 2021). "A potential driving mechanism is that constitutive GTPase activity and the mitogen-activated protein (MAP) kinase signaling pathway are regulated by the recurrent mutant G protein alpha subunit GNAQ and its paralogs GNA11 and GNA14, which are also expressed in other hemangiomas." (PMID 40416971, 2025). "Recent studies have reported the presence of mutually exclusive mutations in GNA14 Q205, GNA11, and GNAQ Q209 in benign hemangiomas, but not in malignant vascular tumors, which supports the histologic impression of THOA." (PMID 39360118, 2024). "Our findings demonstrate that GNA gene (GNAQ, GNA11, GNA14) mutations are a major pathogenetic event in benign vascular proliferations, however, primarily in hemangioma and not vascular malformations." (PMID 34040639, 2021).
iris melanoma (6 papers, 2019 to 2025). A uveal melanoma that arises from the iris. "The fourth patient with a partial response had a GNA11-mutant iris melanoma with a mutational signature indicative of UV damage, which resulted in an outlier tumor mutational burden." (PMID 34453044, 2021). "Mutations that are common in posterior UM such as GNAQ and GNA11 are described in iris melanoma but in lower frequency." (PMID 33396957, 2020). "More iris melanomas have a GNAQ mutation (47%) than a GNA11 mutation (30%)." (PMID 32998469, 2020). "GNAQ, Guanine nucleotide-binding protein subunit alpha-11 (GNA11), EIF1AX, and BAP1 are commonly identified mutations in iris melanoma." (PMID 40491523, 2025). "Iris melanoma harbor GNAQ, GNA11 and EIF1AX mutations while BAP1 mutations and mutations in SF3B1 are less common or rare." (PMID 33396957, 2020). "Iris melanoma, also originating from the uvea, has similarities to the genetic makeups of both posterior uveal melanoma (UM) and conjunctival melanoma since mutations in GNAQ and GNA11 are less common and genes involved in conjunctival melanoma such as BRAF have been described." (PMID 33396957, 2020). "Genetic analysis confirmed our previous observation that patients harboring a wildtype BAP1 gene or who had a UV-damaged iris melanoma lived longer, regardless of their GNAQ/GNA11 mutational status." (PMID 37377898, 2023). "GNAQ and GNA11 are mutually exclusive in iris melanomas, and the mutation status of GNAQ and GNA11 does, similar to UM, not correlate with patient survival." (PMID 32998469, 2020).
blue nevus (5 papers, 2016 to 2026). An intradermal nevus characterized by the presence of benign pigmented dendritic spindle-shaped melanocytes. "Blue nevus often harbors activating mutations in GNAQ and less frequently in GNA11." (PMID 39817262, 2025).
capillary malformation (5 papers, 2020 to 2025). "Recently, the gene mutations of GNAQ and GNA11 have also been detected even in the lesions of sporadic capillary malformation." (PMID 35216474, 2022). "Mutations in GNA11 will lead to malformations and overgrowth of capillary in capillary malformation patients." (PMID 34568004, 2021). "Furthermore, the mechanism by which the mutated GNAQ/GNA11 genes induce capillary malformations is also still unknown, but there are several hypotheses." (PMID 35216474, 2022). "The capillary malformations seen in SWS and the more common isolated, uncomplicated capillary malformations are frequently found to have mutations in GNAQ or GNA11, which can lead to constitutive activation of the RAS/MAPK pathway." (PMID 33194911, 2020). "Indeed, we observed dysregulation of KRIT1, related to cerebral cavernous malformations (CCM), APLN, related to lymphatic malformations, GNA11 related to capillary malformations and BMPR2, related to arteriovenous malformations and hereditary pulmonary arterial hypertension (HHT)." (PMID 38771392, 2024).
Familial hypocalciuric hypercalcemia type 2 (5 papers, 2016 to 2025). "Gna11 is a calcium-sensing receptor, loss of function mutations of which cause familial hypocalciuric hypercalcemia type 2." (PMID 28859164, 2017).
hyperparathyroidism (5 papers, 2017 to 2025). Hyperfunction of the parathyroid glands resulting in the overproduction of parathyroid hormone. "We performed whole exome sequencing in the proband to test for variants in the GNA11 and AP2S1 genes (less common causes of NSHPT) and also analyzed GNPTG as hyperparathyroidism and periosteal changes also occur in I‐cell disease (mucolipidosis Type II)." (PMID 30144375, 2018). "The differential diagnosis consists in the hypocalciuric hypercalcaemia syndrome, types 2 (involving GNA11 gene) and 3 (involving AP2S1 gene); hyperparathyroidism; abnormalities of vitamin D metabolism, involving CYP24A1 and SLC34A1 genes; and reduced GFR." (PMID 28122587, 2017).
hypoparathyroidism (5 papers, 2017 to 2024). Hypoparathyroidism is an endocrine disorder in which the parathyroid glands in the neck do not produce enough parathyroid hormone (PTH). "The role of mutant Gαq protein family members in calcium signaling is highlighted by the presence of inherited germline GNA11 mutations in patients with hypoparathyroidism and hypocalciuric hypercalcemia." (PMID 38618955, 2024). "Molecular analysis of the mutation GNA11 p.R60L, which was identified in a patient with hypoparathyroidism, revealed it is less activating than GNA11 p.Q209L." (PMID 38618955, 2024). "The differential diagnosis consists of the hypercalciuric hypocalcaemia syndrome type 2, involving GNA11 gene and other hypoparathyroidism aetiologies." (PMID 28122587, 2017). "Although hypoparathyroidism and a short stature are caused by many conditions, reports of their coexistence, as in lysine methyltransferase 2D (KMT2D)-related disorders and guanine nucleotide-binding protein subunit alpha 11 (GNA11) variants, are extremely rare." (PMID 36686468, 2022). "Greater than 90% of AIRE mutation-negative probands with suspected familial hypoparathyroidism had apparently isolated hypoparathyroidism, and around 30% of these probands were found to have an abnormality affecting either the CASR, GATA3, GCM2, GNA11 genes or the 22q11.2 chromosomal region." (PMID 35521792, 2022).
vascular malformation (4 papers, 2021 to 2025). A non-neoplastic disorder that is the result of defects of vascular morphogenesis. "And recurrently mutated genes were identified in several vascular malformations as well including TEK/TIE2 mainly in venous malformations, GNA11/14 mainly in vascular tumors, KRAS/NRAS/RASA1/HRAS mainly in AVMs, GNAQ, IDH1/2, AKT1, PTEN and PIK3CA." (PMID 34736485, 2021).
cardiac hypertrophy (3 papers, 2013 to 2022). "Inhibition of guanine nucleotide-binding protein subunit alpha-11, 14, and 15 (GNA-11,14,15), along with GNAQ, inhibits 1-phosphatidylinositol 4,5-bisphosphate phosphodiesterase beta-1, 2, 3, and 4, thus reducing cardiac hypertrophy through EGFR blockade." (PMID 28649439, 2017).